STAG2 (STAG2 cohesin complex component)
Diseases named in the same sentence as STAG2 in open-access papers (continued):
Sharing a sentence is not in itself a finding about the gene and the disease.
cancer (continued). "Additionally, we find that STAG2 mutant cancer cells have increased sensitivity to ionizing radiation and cytotoxic chemotherapeutic agents (e.g., cyclophosphamide and etoposide) that function by inducing DNA double-strand breaks." (PMID 30975996, 2019). "Moreover, we have identified an edge relating the genes with transmembrane protein function with those from the spliceosome (U2AF1, and USP9X) and the cohesin complex (SMC1A and STAG2) that have an important role in cancer." (PMID 26886259, 2016). "The fact that the missense mutations tested retained wild-type cohesion, mitotic integrity, and ploidy suggests that perhaps these phenotypes are not central to the cancer-causing effects of STAG2 mutations." (PMID 26871722, 2016). "In addition to STAG2, other recurrent alterations in subunits of this complex have been reported across a number of cancer types." (PMID 25010205, 2014). "Other gene silencing mechanisms might contribute as STAG2 protein was lost in 23-30% of studied carcinomas." (PMID 24088605, 2013). "Importantly, STAG2 expression correlates with poor prognosis of cancer patients." (PMID 37985839, 2023). "However, the exact mechanism by which STAG2 drives or suppresses cancer pathogenesis remains unknown." (PMID 35371307, 2022). "Our findings not only establish a previously unknown role of the STAG2 to STAG1 switch in 3D genome organization, but also reveal a functional link between STAG2 and interferon signaling in cancer cells, which may enhance the immune evasion potential in STAG2-mutant cancer." (PMID 35388001, 2022). "Finally, we identified putative pathogenic alterations in multiple cancer genes, including genes involved in epigenome editing and 3D genome organization, such as EP300, CTCF, and STAG2, which we validated by targeted sequencing of an independent cohort of 115 BM samples." (PMID 36561283, 2022). "Notably, the ratio of Stag2 transcripts to Stag1 transcripts in wild-type mESCs is 1.08, which is lower than most of the ~ 1000 cell lines in the Cancer Cell Line Encyclopedia, indicating that other cell types operate with a relatively higher level of cohesin-STAG2 than cohesin-STAG1." (PMID 32778134, 2020). "Finally, we asked whether the reported synthetic lethality observed upon depletion of STAG1 in STAG2-null cancer cells also occurred in mESCs." (PMID 32778134, 2020). "While cancer-associated mutations in genes encoding RAD21, SMC3, and STAG1 are always heterozygous, mutations in the X chromosome-located genes SMC1A and STAG2 can result in complete loss of function due to hemizygosity (males), or silencing of the wild type during X-inactivation (females)." (PMID 33284104, 2020). "Additionally, we found that the levels of SMC3 acetylation were impaired in cancer cells lines harboring STAG2 inactivation (H4 parental and TC-106 STAG2 knockout cells) relative to their STAG2 wildtype counterparts (H4 STAG2 knock-in and TC-106 parental cells)." (PMID 30975996, 2019). "STAG2 loss of function was reported in different cancers but not in IBC." (PMID 30086764, 2018). "It is not clear exactly how mutations that affect STAG2 make cancer more likely to develop." (PMID 28691904, 2017). "We also found that other known cancer-related genes were also altered at low frequency including APC (n = 5), KRAS (n = 2), SETD2 (n = 2), DAXX (n = 1) and STAG2 (n = 1)." (PMID 37524847, 2023). "Identifying a number of putative drivers, ARID1A, CHD4, HCFC1, STAG2, SMARCA4, and NCOR1 are known cancer driver genes." (PMID 37444571, 2023). "Taken together, these data suggest that BUB1, STAG2, SMC3, and THOC1 function in cell growth, proliferation, and tumorigenesis and thus play crucial roles in cancer development." (PMID 32518584, 2020).
cancer (continued). "To validate the predicted synthetic lethal interaction between STAG1 and STAG2, we inactivated them in the CAL-51 cancer cell line where both genes are WT." (PMID 28430577, 2017). "By quantifying cancer genome evolution using the gene gravity model, we identified six putative cancer genes (AHNAK, COL11A1, DDX3X, FAT4, STAG2, and SYNE1)." (PMID 26352260, 2015). "Cancer cells depend on the overlapping function of STAG1 in STAG2 knockout cell lines to maintain the integrity of chromatin cohesion; double knockout of STAG1 and STAG2 induces synthetic lethality." (PMID 37444402, 2023). "As expected, the network demonstrated that STAG2 and RAD21 could cross-talk with other modules, such as TGF-β signaling, pathway in cancer, the pluripotency of stem cells, and adenocarcinoma, in addition to the cell cycle." (PMID 35371307, 2022). "We were not able to validate the association of STAG2- and CRTC3-related signatures with survival in ER-positive/HER2-negative cancers due to the lack of the probe sets specific for these signatures in the Illumina gene chips." (PMID 29559730, 2018). "Although we did not detect any full-length protein, STAG2 mRNA is still expressed in SK-ES-cells according to the gene expression profile of the cancer cell line project." (PMID 28430577, 2017). "STAG1 inactivation has little if any impact on the viability and proliferation of STAG2 wild-type cancer cells and non-transformed cells, but is essential for survival in the absence of STAG2." (PMID 28691904, 2017). "Also, genes STAG2 and U2AF1 were detected as drivers in AML and SMC1A in distinct cancers by the IntOGen tool." (PMID 26886259, 2016). "Although paralogous synthetic lethal pairs like STAG1/STAG2 and IREB2/ACO1 are interesting biologically, how the large therapeutic window of these paralogous synthetic lethal interactions can be translated into potential cancer therapeutics is an open question." (PMID 34462321, 2021). "However, the high selectivity of StagX1 in blocking the growth of mutant STAG2 EwS cells but not the growth of all other types of cancer cells may provide StagX1 an advantage for use as a specific therapeutic agent." (PMID 35740349, 2022).
tumor (80 papers, 2013 to 2026). "Expression of stromal antigen 2 (STAG2), a member of the cohesin complex, is associated with aggressive tumor characteristics and worse clinical outcomes in muscle invasive bladder cancer (MIBC) patients." (PMID 40025053, 2025). "It has been suggested that STAG2 LOF increases the chance that mutated cells acquire tumor-driving mutations by extending cell life span." (PMID 35287703, 2022). "Within this cohort, 0/17 patients with STAG2 expressing tumours by IHC had deleterious STAG2 mutations." (PMID 36221002, 2022). "Approximately 85% of STAG2 mutations are truncating and often result in loss of expression, indicating STAG2 as a tumor suppressor gene." (PMID 35287703, 2022). "Altogether, these results indicate that STAG2 loss slowed tumor growth which resulted in smaller endpoint tumor weights in vivo." (PMID 36275363, 2022). "Further investigation of specific STAG2 mutations is required to fully define these tumor-promoting functions." (PMID 36275363, 2022). "To investigate the prevalence of STAG2 mutations, we performed whole-exome and targeted sequencing (n = 119) of tumor tissues from patients with MIBC." (PMID 36275363, 2022). "Clinically, STAG2 loss is associated with lower tumor grade and stage in patients with NMIBC and MIBC." (PMID 36275363, 2022). "Results from next-generation sequencing (NGS) of the primary tumor detected STAG2 R216 mutation, predicting genome instability and potential response to platinum-based chemotherapy and olaparib." (PMID 33706745, 2021). "In some tumors, STAG2 loss was subclonal in the primary tumor, but characterized the main clone in the metastases." (PMID 33919988, 2021). "A similar decrease in pluripotency was also observed in mouse ES cells deficient for Stag1/2, or with tumor-derived cohesin mutations in Stag2 or Smc1a." (PMID 34202641, 2021). "Tumor DNA sequencing has shown that STAG2 mutations or chromoplexy‐associated fusion gene genesis is associated with more aggressive clinical behavior." (PMID 32115849, 2020). "STAG2 mutations are frequently detected in multiple tumor types and its loss of function is believed to induce aneuploidy." (PMID 29662124, 2018). "The deleterious nature of most STAG2 mutations strongly suggests that the gene represents a new tumor suppressor." (PMID 28691904, 2017). "In an effort to provide insight into these discrepancies, here we analyze the effect of tumor-derived STAG2 mutations on the protein composition of cohesin and the expected mitotic phenotypes of STAG2 mutation." (PMID 26871722, 2016). "For example, our reported functional studies of tumor-derived STAG2 mutations have been primarily limited to two truncating mutations present in the human H4 and 42MGBA GBM cell lines (which were corrected by human somatic cell gene targeting)." (PMID 26871722, 2016). "We next determined the boundary in STAG2 protein at which tumor-derived truncating mutations retained their ability to interact with cohesin." (PMID 26871722, 2016). "All tumor-derived nonsense mutations in STAG2 led to a reduction in the integrity of sister chromatid cohesion." (PMID 26871722, 2016). "We then created and studied isogenic sets of human cells in which the endogenous allele of STAG2 was modified via the addition of nine different tumor-derived mutations." (PMID 26871722, 2016). "In two previous studies, we found that introduction of a non-tumor derived mutation or stable lentiviral depletion of wild-type STAG2 led to alterations in chromosome counts in human cells–in both cases increasing the modal chromosome number by one." (PMID 26871722, 2016). "To express tumor-derived STAG2 mutations in human cells, we created a full length human STAG2 expression vector with a 1x FLAG/Streptavidin Binding Peptide (SBP) dual epitope tag at the amino terminus." (PMID 26871722, 2016).
tumor (continued). "Many of the mutations led to virtually complete loss of expression of the encoded protein, consistent with the expectation that STAG2 genes harboring tumor-derived nonsense mutations produce transcripts that are degraded by nonsense mediated decay." (PMID 26871722, 2016). "Taken together, these data indicate that the presence of tumor-derived STAG2 mutations results in a decrease in levels of cohesin and a reduction in ability of WAPL, PDS5A, and PDS5B to interact with cohesin." (PMID 26871722, 2016). "Using these isogenic sets of cells, we next tested the effect of tumor-derived nonsense and missense mutations in STAG2 on sister chromatid cohesion, mitotic fidelity, and chromosome counts." (PMID 26871722, 2016). "Approximately 85% of tumor-derived STAG2 mutations lead to premature truncation of the encoded protein, whereas approximately ~15% are missense mutations." (PMID 26871722, 2016). "Next, we used human somatic cell gene targeting to introduce a subset of these tumor-derived mutations into the endogenous allele of STAG2 in a chromosomally stable, near diploid human cell line." (PMID 26871722, 2016). "Using AAV-mediated gene targeting, we then introduced nine tumor-derived mutations into the endogenous allele of STAG2 in cultured human cells." (PMID 26871722, 2016). "Here we report a comprehensive analysis of the effects of tumor-derived STAG2 mutations on the composition of cohesin and on mitotic phenotypes generally attributed to cohesin inactivation." (PMID 26871722, 2016). "To do this, we created nine additional tumor-derived truncating mutations in STAG2 from amino acid 1021 to amino acid 1137 in the cloned STAG2 expression vector (#51–59), transfected 293T cells, and performed IP-Western blotting." (PMID 26871722, 2016). "In the studies presented here we have focused our attention on the role of tumor-derived mutations in STAG2 on the protein composition of cohesin, cellular proliferation, mitosis, and aneuploidy." (PMID 26871722, 2016). "In tumor samples, all evaluable STAG2 mutated samples showed preferential RNA expression of the mutant allele with varying amounts of wild type allele (median variant allele frequency 0.78), likely due to varying amounts of normal tissue contamination." (PMID 25010205, 2014). "Here we report the mutation spectrum and the relationship of loss of STAG2 expression with gender, tumour grade, stage and chromosomal stability." (PMID 24270882, 2014). "As expected, given the association of STAG2 mutation with low tumour grade and stage, we also found significant association with these other mutational events in the non-invasive tumour group." (PMID 24270882, 2014). "As is widely reported, these were more common in tumours of high grade and stage where STAG2 mutation was less common." (PMID 24270882, 2014). "This measure was also significantly lower in tumours with STAG2 mutation (Mann–Whitney U-test, P < 0.002)." (PMID 24270882, 2014). "Aneuploidy is also frequently observed in other malignancies and recently STAG2 was recognized as a tumor suppressor gene causing malfunctioning mitotic sister chromatid separation when inactivated." (PMID 24088605, 2013). "Consequently, by age 70, 100% (CI: 71 to 146%) of inactivating STAG2 mutations in tumours can be explained as passenger events." (PMID 39920335, 2025).
tumor (continued). "However, we did observe a positive association between STAG2 mutation and tumor volume, whereby tumor volumes ≥200 mL were associated with an 8.58-fold increase in the odds of an STAG2 mutation." (PMID 41183255, 2025). "Finally, a subset of tumor-derived STAG2 mutations was introduced into human cells to analyze the chromosome counts." (PMID 39594644, 2024). "Once validated in an independent cohort, STAG2 expression could be incorporated in a prospective trial studying novel treatments for patients with high-risk localised tumours." (PMID 36221002, 2022). "This further emphasizes the importance of categorizing tumor samples by level of STAG2 protein expression instead of mutational status to account for epigenetic or post translational modifications which may ultimately affect expression." (PMID 36275363, 2022). "In fact, STAG2 is 1 of only 12 genes significantly recurrently mutated in four or more tumour types although how STAG2 loss-of-function might promote tumourigenesis remains unclear." (PMID 34462321, 2021). "This makes STAG2 loss an attractive patient selection biomarker, which if targeted by precision medicine might allow for the eradication of most tumor cells." (PMID 32467316, 2020). "To test these hypotheses, we expressed 59 tumor-derived mutations in human cells in an epitope tagged STAG2 cDNA." (PMID 26871722, 2016). "Arguably the most straightforward hypothesis regarding the loss of activity caused by tumor-derived STAG2 mutations is that the mutations abolish the ability of the encoded STAG2 protein to interact with the rest of the cohesin complex." (PMID 26871722, 2016). "The chromosome counting data presented here are especially surprising in light of our previously published data showing that the introduction of an amino terminal, non-tumor derived truncating mutation into STAG2 leads to an increase in modal chromosome number." (PMID 26871722, 2016). "Of note, we have previously used a similar approach to KI a single, non-tumor derived amino terminal nonsense mutation at codon six into STAG2 in HCT116 cells and demonstrated a substantial reduction in sister chromatid cohesion and alterations in chromosome counts." (PMID 26871722, 2016). "Next, we tested whether cells harboring tumor-derived mutations in STAG2 showed a reduction in the integrity of sister chromatid segregation during anaphase." (PMID 26871722, 2016). "Taken together, these data demonstrate that tumor-derived mutations of STAG2 do not uniformly lose the ability to interact with cohesin, indicating that at least some tumor-derived mutations of STAG2 must affect a key function of STAG2 other than its ability to interact with cohesin." (PMID 26871722, 2016). "Somatic mutations of the cohesin complex subunit STAG2 are present in diverse tumor types." (PMID 26871722, 2016). "STAG2 protein detection by IHC in an independent tumor cohort showed STAG2 loss in 14.3% of tumors." (PMID 25010205, 2014). "We assessed the relationship of STAG2 mutation with tumour grade, stage and patient gender." (PMID 24270882, 2014). "We have also shown that high tumor STAG2 protein expression, specifically in MIBC patients, is associated with significantly worse survival outcomes and an invasive phenotype." (PMID 40025053, 2025). "Here, we demonstrated that tumor cell lines with STAG2 defect are hypersensitive to ATM inhibitors as well as other DNA damage response‐related stimuli (e.g., irradiation, camptothecin, and cisplatin)." (PMID 37985839, 2023). "More importantly, we found that tumor cells with STAG2‐knockout can be also selectively killed by an inhibitor of poly ADP ribose polymerase (PARPi), especially when combined with ATMi." (PMID 37985839, 2023). "These were commonly male patients with local tumours and mutations in VHL and wild-type FAT1 and STAG2." (PMID 37391505, 2023).